RAB6B (RAB6B, member RAS oncogene family)
Description:
The small GTPases Rab are key regulators of intracellular membrane trafficking, from the formation of transport vesicles to their fusion with membranes. Rabs cycle between active GTP-bound and inactive GDP-bound states. In their active state, drive transport of vesicular carriers from donor organelles to acceptor organelles to regulate the membrane traffic that maintains organelle identity and morphology (By similarity). Recruits VPS13B to the Golgi membrane. Regulates the compacted morphology of the Golgi. Seems to have a role in retrograde membrane traffic at the level of the Golgi complex. May function in retrograde transport in neuronal cells. Plays a role in neuron projection development.
Tractability: Small molecule: a structure with a bound ligand is known; it has a binding pocket of medium quality. PROTAC: ubiquitination databases record sites on it; its protein half-life has been measured.
Gene: Protein-coding gene on chromosome 3 (133,824,235 to 133,895,882, reverse strand). Ensembl gene ENSG00000154917.
Subcellular location: Golgi apparatus membrane; Endoplasmic reticulum-Golgi intermediate compartment; Cytoplasmic vesicle
Subcellular location (Human Protein Atlas): Golgi apparatus; Basal body
Pathways (Reactome):
Vesicle-mediated transport: COPI-independent Golgi-to-ER retrograde traffic; RAB GEFs exchange GTP for GDP on RABs; Retrograde transport at the Trans-Golgi-Network; TBC/RABGAPs
Metabolism of proteins: RAB geranylgeranylation
Gene Ontology:
Molecular function: G protein activity; myosin V binding; protein binding; GTPase activity; GTP binding
Biological process: Golgi organization; protein localization to Golgi membrane; intra-Golgi vesicle-mediated transport; neuron projection development; retrograde transport, endosome to Golgi; retrograde vesicle-mediated transport, Golgi to endoplasmic reticulum
Cellular component: cytoplasmic vesicle; endoplasmic reticulum-Golgi intermediate compartment; Golgi apparatus; Golgi membrane; cytosol
Genetic constraint (gnomAD): Loss-of-function variants: 7 observed, 32.64 expected, observed/expected ratio (o/e) 0.21, 90% interval 0.12 to 0.4. The upper end of that interval is the gene's LOEUF score, 0.4, which puts it in group 1 of 6, group 1 being the genes least tolerant of losing a copy. Missense variants: 149 observed, 293.58 expected, observed/expected ratio (o/e) 0.51, 90% interval 0.44 to 0.58. Synonymous variants: 105 observed, 110.46 expected, observed/expected ratio (o/e) 0.95, 90% interval 0.81 to 1.12.
Homologues: Orthologues: chimpanzee RAB6B (100% identical), dog RAB6B (100% identical), guinea pig RAB6B (100% identical), macaque RAB6B (100% identical), mouse Rab6b (100% identical), zebrafish rab6ba (96% identical), pig RAB6B (85% identical), rat Rab6b (84% identical), Caenorhabditis elegans rab-6.2 (77% identical), rabbit RAB6B (77% identical). Paralogues in human: RAB6A (90% identical), RAB6D (82% identical), RAB6C (81% identical), RAB41 (65% identical), RAB5A (41% identical), RAB26 (40% identical), RAB8B (40% identical), RAB37 (40% identical), RAB5C (40% identical), RAB5B (39% identical), RAB8A (39% identical), RAB10 (38% identical), and 56 more.
Diseases named in the same sentence as RAB6B in open-access papers:
RAB6B is named in the same sentence as 18 diseases in open-access papers, as found by Europe PMC text mining. Sharing a sentence is not in itself a finding about the gene and the disease. The quoted sentences say what the papers report.
gastric cancer (4 papers, 2021 to 2025). A primary or metastatic malignant neoplasm involving the stomach. "Recently, studies have shown that RAB6B expression in gastric cancer can promote tumor cells proliferation, while RAB6B is low expressed and associated with poor prognosis in pancreatic cancer patients, suggesting that the role of RAB6B is context-specific." (PMID 36120364, 2022). "In gastric cancer cells, miR-4268 expression negatively correlated with Rab6B expression, and miR-4268 overexpression repressed gastric cancer cell growth." (PMID 34281234, 2021). "Prior study has shown that high RAB6B expression promoted cell proliferation and the cell cycle G1/S phase transition through AKT/JNK signaling pathways in gastric cancer." (PMID 36120364, 2022). "Silencing RAB6B in gastric cancer inhibits the AKT/JNK signaling pathway, suppressing gastric cancer cell proliferation, and impels apoptosis by furthering the p38 MAPK pathway." (PMID 33937013, 2021).
melanoma (3 papers, 2012 to 2023). A malignant, usually aggressive tumor composed of atypical, neoplastic melanocytes. "Among differentially expressed splice variants in the comparison of melanomas with benign melanocytic nevi, RAB6B, a member of the RAS oncogene family, was the top gene with differentially expressed spliced variants between benign and malignant lesions." (PMID 34281234, 2021). "The dominant variant found in melanoma was characterized by an intron loss, which may lead to reactivation of the RAB6B gene and may thereby exert pro-tumorigenic functions." (PMID 34281234, 2021). "Among the top genes with differentially spliced isoforms between primary melanomas and benign melanocytic nevi were RAB6B, MSR1, LYPD1, and COL11A2." (PMID 34281234, 2021). "Thus, this RAB6B isoform in melanomas may exert pro-tumorigenic functions." (PMID 34281234, 2021). "Thus, RAB6B, REL and WHSC1L1, as identified by our analysis, may represent additional oncogenes for melanoma." (PMID 22295108, 2012).
asthma (1 paper, 2019). "With regards the unmet need for asthma biomarkers, we identified various mRNAs in the circulation that were uniquely expressed in the asthmatic subjects, including HIST1H3C, PRAM1, RAB6B and CD93." (PMID 31221987, 2019).
colon cancer (1 paper, 2022). "Rab6B, whose family member affects the regulation of intracellular transport routes, has been known as an oncogene in colon cancer." (PMID 35464857, 2022).
colorectal cancer (1 paper, 2022). A primary or metastatic malignant neoplasm that affects the colon or rectum. "By contrast, RAB6B was low expressed in pancreatic and colorectal cancers, and correlated with poorer prognosis in patients." (PMID 36120364, 2022).
glioma (1 paper, 2023). A benign or malignant brain and spinal cord tumor that arises from glial cells (astrocytes, oligodendrocytes, ependymal cells). "Each glioma patient was assigned a risk score according to the following formula: risk score = (0.2433)*RAB13 + (0.4201)*LYPLA1 + (0.0013)*GAS1 + (−0.0463)*VAMP2 + (0.5165)*CNIH4 + (0.3109)*PICK1 + (−0.0864)*RAB6B + (0.0978)*GOLT1." (PMID 37062068, 2023).
liver cancer (1 paper, 2022). An epithelial or non-epithelial malignant neoplasm that arises from the liver. "Therefore, we explored the proportion and types of RAB6B mutations in liver cancer." (PMID 36120364, 2022).
prion disease (1 paper, 2024). A transmissible disease that is caused by a protein that is able to induce abnormal folding of normal cellular proteins, leading to characteristic spongiform brain changes, which are associated with neuronal loss without an inflammatory response. "Rbm3 upregulation combined with decreased Egr1 and Rab6b was readily detected at the clinical endpoint of prion disease, but not at earlier timepoints." (PMID 39580485, 2024).
schizophrenia (1 paper, 2023). A major psychotic disorder characterized by abnormalities in the perception or expression of reality. "Here these two proteins, RAB6B and RAB7A, were found altered in the prefrontal cortex in schizophrenia with an interaction with both ACTR1A and DCTN5." (PMID 37033658, 2023).
cancer (5 papers, 2018 to 2022). A tumor composed of atypical neoplastic, often pleomorphic cells that invade other tissues. "The correlations between RAB6B and tumor-infiltrating immune cells and cancer-associated fibroblasts were explored by using TIMER, TISIDB, and GEPIA databases." (PMID 36120364, 2022). "Evidence for a role of RAB6B in cancer development is scarce, but the gene has been shown to be involved in GTP binding and may function in the retrograde Golgi transport in neuronal cells." (PMID 34281234, 2021). "Furthermore, our results are confirmed by the literatures, with 6 out of top 10 features associated with specific cancers including NKIRAS1, CDKN2B, YTHDC2, MECOM, RBFOX1, and RAB6B." (PMID 33329723, 2020). "This last group included genes involved in cell migration and ECM (e.g. RAB6B, FN1, VCAM1 or COL14A1) and genes of signalling pathways usually deregulated in cancer, such as Notch and Wnt signalling (JAG1 and WNT7B, respectively)." (PMID 34353313, 2021). "The exact functions of the other two putative KEAP1-NRF2-CUL3axis-regulated genes, RAB6B and TRIM16L, are unknown in cancer cells and therefore are under investigation in our lab." (PMID 29306329, 2018).
tumor (5 papers, 2021 to 2024). "Meanwhile, RAB6B expression was related to the infiltrating abundance of various tumor-associated immune cells in HCC, including B cells, CD8+ T cells, CD4+ T cells, macrophages, neutrophils, and DCs." (PMID 36120364, 2022). "The correlation between RAB6B expression and tumor lymphocyte infiltration in HCC (TISIDB)." (PMID 36120364, 2022). "All these results indicated that the RAB6B co-expression network may influence the tumor stroma in the TME of HCC." (PMID 36120364, 2022). "Therefore, the relationship between RAB6B expression and tumor immune-infiltrating immune cells in HCC was explored." (PMID 36120364, 2022). "The functional enrichment results showed that RAB6B may be associated with ECM remodeling in the TME, so we explored the regulatory role of RAB6B on tumor stroma." (PMID 36120364, 2022). "Therefore, we here mainly explored the potential functions of RAB6B in HCC based on public databases, including its role in tumor-associated immune cells infiltration and tumor stroma remodeling." (PMID 36120364, 2022). "Our analysis identified seven tumour suppressor genes (ITGA7, SLC45A1, TPPP, SCN4A, GIPR, SOGA3 and RAB6B) and six oncogenes (SAT1, SERPINE1, UPK2, SYT12, RASAL1 and CDH3) with significant false discovery rate (FDR)-adjusted P values (q-value) of less than 0.05." (PMID 38429478, 2024). "While ectopic expression of RAB6B, or RAB27A, partially reversed the observed statin sensitivity, co-expression of RAB6B and RAB27A essentially rescued growth inhibition by statin treatment, as demonstrated using in vitro cell proliferation and in vivo tumor xenograft growth measures." (PMID 37277330, 2023). "Microarray profiles comparing GSLCs and non-stem tumor cells (NSTCs) isolated from primary human GBM (GBM-1) showed that 4 out of 100 members in the Ras-superfamily (RAB26, RAB27B, RAB6B and ARL4C) were significantly up-regulated in GSLCs (P < 0.05)." (PMID 33403039, 2021).
RAB6B also shares sentences with these, for which no sentence is quoted: hepatocellular carcinoma (2 papers); breast carcinoma (1); COVID-19 (1); infection (1); myocardial infarction (1); pancreatic cancer (1); pneumonia (1).